REN (renin)
Diseases named in the same sentence as REN in open-access papers (continued):
Sharing a sentence is not in itself a finding about the gene and the disease.
asthma (14 papers, 2009 to 2025). "Furthermore, six significant pathways enriched in the low-risk group (allograft rejection, asthma, hematopoietic cell lineage, intestinal immune network for IgA production, renin-angi system, viral myocarditis)." (PMID 37456238, 2023). "A hormonal pathway called the renin–angiotensin–aldosterone system (RAAS) appears to play a role in the inflammatory processes and airway remodeling associated with asthma." (PMID 40867700, 2025). "The renin–angiotensin–aldosterone system (RAAS) plays a crucial role in asthma pathophysiology in murine models." (PMID 40867700, 2025). "The clinical relevance of these findings is supported by observations in humans, which show elevated plasma renin and AngII levels during severe asthma attacks and AngII-induced bronchoconstriction in mild asthma patients." (PMID 40867700, 2025). "Experimental and clinical studies have demonstrated that the renin–angiotensin system (RAS) is a key modulator involved in the pathophysiology of asthma in a murine model." (PMID 40867700, 2025). "Elevated levels of AngII and renin have been reported in patients with severe, acute asthma, with higher plasma concentrations observed during exacerbations compared to healthy controls." (PMID 40867700, 2025). "When evaluating asthma in the context of cardiology, it is essential to consider the role of the renin–angiotensin–aldosterone system (RAAS), which serves as a primary regulator of cardiovascular and fluid–electrolyte homeostasis." (PMID 40867700, 2025). "The renin–angiotensin–aldosterone system (RAAS) plays a crucial role in asthma pathophysiology, particularly through angiotensin II’s effects on airway inflammation and remodeling." (PMID 40867700, 2025). "These pathways include the renin-angiotensin system, immune checkpoint signaling, NK cell-mediated cytotoxicity, asthma, and allograft rejection." (PMID 39781341, 2025). "GSEA analysis based on the KEGG gene set showed that the terms of the renin-angiotensin system, asthma, histidine metabolism were significantly upregulated in patients with high SLC40A1 expression." (PMID 37740815, 2023). "GSEA showed significantly positive enrichment of the Fc epsilon RI pathway, asthma, vascular smooth muscle contraction, T cell receptor signaling, B cell receptor signaling, renin-angiotensin-aldosterone system, and VEGF signaling pathways in the low-risk group." (PMID 34745939, 2021). "In patients with acute severe asthma, the renin-angiotensin system is activated." (PMID 31485240, 2019). "Asthma and COPD are well-established diseases of immune response, and evidence has linked these conditions with the autonomic and immune systems in addition to demonstrating that the renin–angiotensin system is activated in severe asthma." (PMID 19590686, 2009). "Preliminary evidence from smaller studies suggests possible roles for autonomic dysfunction and renin-angiotensin pathway involvement in linking GERD and asthma." (PMID 41583298, 2025).
gout (14 papers, 2010 to 2025). A condition characterized by painful swelling of the joints, which is caused by deposition of urate crystals. "All patients reported with REN pathogenic variants have presented after the age of 20 years, often with gout." (PMID 39722771, 2024). "On the other hand, a mutation in part of the mature renin protein presents in adult-onset CKD and gout, with patients reaching ESKD in their late 60s." (PMID 36362756, 2022). "We investigate here whether a dysregulation of the renin-angiotensin system, and in particular an action at the AT2R, may also be responsible for the pain and inflammation observed in gout." (PMID 36173505, 2022). "However, there are no studies to date evaluating the possible involvement of renin-angiotensin system in gout." (PMID 36173505, 2022).
Hepatic steatosis (14 papers, 2013 to 2025). Steatosis is a term used to denote lipid accumulation within hepatocytes. "On the other hand, aliskiren has been proved as an effective way to block renin activity and restrain liver steatosis and fibrosis in different models of murine NASH." (PMID 29046730, 2017). "Recently, aliskiren, the first renin inhibitor to be approved for clinical use, has been reported to reduce hepatic steatosis." (PMID 26732252, 2016). "Renin inhibitors have also been shown to reduce hepatic steatosis and fibrosis in NAFLD mice." (PMID 39334685, 2024). "Previous studies determined that hepatocyte-specific deficiency of angiotensinogen (AGT), the unique substrate of the renin-angiotensin system (RAS), alleviates WD-induced hepatic steatosis in mice." (PMID 40687776, 2025). "As a component of the renin-angiotensin system (RAS), ACE2 mitigates the pro-inflammatory and pro-fibrotic effects of angiotensin II, and its elevation in fatty liver disease may reflect a protective, compensatory adaptation to lipid overload and oxidative stress." (PMID 40502600, 2025). "Interestingly, blocking the renin-angiotensin system by Valsartan did not result in fatty liver." (PMID 23837919, 2013).
liver cirrhosis (14 papers, 2010 to 2024). "In patients with liver cirrhosis, the progression of vasodilatation activates vasoconstrictive systems, and the activation of the renin–angiotensin system results in renal vasoconstriction and renal blood flow decrease." (PMID 39336986, 2024). "Sodium retention in liver cirrhosis due to the activation of the renin-angiotensin-aldosterone system (RAAS) partly explains the reason for diastolic dysfunction in patients with liver cirrhosis." (PMID 38694655, 2024). "This study found that systemic inflammation already exists when liver cirrhosis is decompensated, manifested by increased plasma inflammatory factors, renin and copeptin." (PMID 35399641, 2022). "It has been reported that the level of renin is elevated in liver cirrhosis, HCC, and hepatoblastoma." (PMID 33639034, 2021). "Cardiovascular disease, type 2 DM and liver cirrhosis have been strongly considered as risk factors of CKD because of inflammation, ischemia, hemodynamic change, and the overactivity of renin–angiotensin–aldosterone and sympathetic nervous systems." (PMID 32915865, 2020). "In patients with advanced liver cirrhosis, arterial pressure is maintained by multiple vasoconstrictive systems, including the renin–angiotensin–aldosterone system and the sympathetic nervous system, and the antidiuretic hormone." (PMID 31687012, 2019).
Renal artery stenosis (14 papers, 2019 to 2026). The presence of stenosis of the renal artery. "Vessel involvement is likely to reflect on the dynamics between TA and pregnancy as fetal complications such as IUGR and oligohydramnios are associated with renal artery stenosis, due to increased renin activity and resultant elevation of blood pressure and uteroplacental insufficiency." (PMID 37006845, 2023). "3-1 [CQ] Are renin–angiotensin–aldosterone system (RAAS) inhibitors recommended more than other antihypertensive drugs for CKD with renal artery stenosis?" (PMID 38713253, 2024). "Distinctly, the diagnosis of hyponatremic hypertensive syndrome secondary to unilateral renal artery stenosis was confirmed in light of laboratory and radiographic findings of severe natriuresis, elevated renin, and unilateral small kidney." (PMID 30791890, 2019). "Renal artery stenosis may commonly occur due to Takayasu disease; however, the resulting accentuation of the renin-angiotensin-aldosterone cascade and increased intraglomerular pressure may cause focal segmental glomerulosclerosis." (PMID 41767684, 2026). "Secondary hyperaldosteronism, characterized by high levels of aldosterone and renin, can be due to a multitude of causes, including renal artery stenosis, and presents with nonspecific symptoms of fatigue, increased thirst, and muscle spasms." (PMID 36049207, 2022). "Because renal artery stenosis (RAS) often presents bilateral, we sought to investigate the renal pressure‐flow relationship and its relation to renin release, in the presence of a contralateral significant stenosis." (PMID 39613722, 2024).
artery stenosis (13 papers, 2014 to 2025). "The initial reduction in renal blood flow associated with renal artery stenosis (RAS) leads to activation of the renin-angiotension-aldosterone system (RAAS), a physiological response that leads to increase in MAP in order to restore perfusion pressure in the kidney beyond the stenosis." (PMID 34070611, 2021). "The pathogenesis of HHS begins with unmitigated renin release from a chronically ischemic kidney, most commonly in the setting of unilateral renal artery stenosis." (PMID 39364484, 2024). "Poor weight gain also occurs in humans with unilateral renal arterial stenosis, high renin concentrations, and increased blood pressure." (PMID 25140254, 2014). "Once renal artery stenosis occurs, it may lead to the activation of the renin-angiotensin system, and blood pressure is more difficult to control." (PMID 38243321, 2024). "The coexistence of PHEO and hyperreninemia secondary to renal artery stenosis has been previously reported, while only a paper, which described a 18 years follow-up in a family affected by MEN 2 B, found the association between adrenal medullary hyperplasia and renin-secreting juxtaglomerular tumor." (PMID 26084817, 2015). "This study found that not all children had elevated blood renin levels, which was inconsistent with the severity of renal artery stenosis." (PMID 36461036, 2022).
autonomic dysfunction (13 papers, 2013 to 2025). "This is partly due to autonomic dysfunction being associated with altered vascular adrenoceptor sensitivity and catecholamine release, altered renin release and the concurrent development of arterial stiffness and other diabetic complications." (PMID 23978271, 2013). "In addition to psychological distress, the presence of multiple PS stressors in AF patients with CD might be linked to underlying systemic inflammation, autonomic dysfunction, or dysregulation of the renin–angiotensin–aldosterone and hypothalamic–pituitary–adrenal axes." (PMID 40805894, 2025). "SARS-CoV-2 infection can trigger severe autonomic dysfunction due to autoantibodies targeting the autonomic nervous system and the renin-angiotensin-aldosterone system." (PMID 39840012, 2024). "In the heart, MR overactivation favours arrhythmia and aldosterone/renin ratio was associated with heart rate variability (HRV), a surrogate of autonomic dysfunction." (PMID 37682293, 2023). "Dysregulation of the compensatory mechanisms to increase cardiac output, namely sympathetic and renin–angiotensin–aldosterone system activation create autonomic dysfunction, is a known etiology for inappropriate ST." (PMID 36057572, 2022). "For example, adrenal angiotensinogen was shown to be activated by adrenal renin in autonomic dysfunction." (PMID 28732007, 2017). "Combined with the data showing a decrease of adrenal renin expression during the development of autonomic dysfunction, our analyses suggest that adrenal renin downregulation may drive the onset of autonomic dysfunction through the disinhibition of AT1R expression in the brainstem." (PMID 28732007, 2017).
Bartter syndrome (13 papers, 2011 to 2025). "Reports have indicated the onset of focal segmental glomerulosclerosis (FSGS) in Bartter syndrome due to the continued activation of the renin-angiotensin system, leading to secondary chronic glomerular hyperfiltration." (PMID 39588405, 2024). "The importance of the Cox-2/PGE2/EP axis for renin expression is further supported by the successful treatment of hyperreninemia with Cox-2 inhibitors in patients with Bartter syndrome." (PMID 35511367, 2022). "Transformation of extraglomerular mesangial cells to renin-producing cells is often observed in situations of chronic salt wasting, for example, due to genetic defects in the aldosterone synthase or in chloride channels, as in Bartter syndrome." (PMID 35511367, 2022). "Gitelman’s syndrome (GS) and Bartter’s syndrome (BS) are two salt-losing tubulopathies characterized by hypokalemic metabolic alkalosis with high activation of the renin–angiotensin–aldosterone system, with high renin and aldosterone levels yet hypotension or normotension." (PMID 34578838, 2021). "Because luminal chloride sensing is defective in Bartter syndrome, the MD behaves as if chloride delivery is low, leading to protracted PGE2 synthesis and high levels of renin." (PMID 35069250, 2021).
Cognitive impairment (13 papers, 2015 to 2025). Abnormal cognition is characterized by deficits in thinking, reasoning, or remembering. "Evidence has suggested that, in certain instances, the pro-renin binds with the pro-renin receptors instead of binding to renin, leading to angiotensinogen cleavage and overactivation of angiotensin receptors, causing cognitive impairment." (PMID 34827667, 2021). "Activation of the renin–angiotensin system has also been suggested to be involved in cognitive impairment through possible contributors including oxidative stress, inflammation, platelet aggregation and vasoconstriction." (PMID 39980672, 2025). "More studies reported that both renin and angiotensinogen have been detected in brain cells, stimulating renin signaling and determining cognitive impairment by activation of angiotensin receptors." (PMID 32824404, 2020). "And the brain renin-angiotensin-aldosterone system (RAAS) may serve as a bridge connecting renal dysfunction in DKD with cognitive impairment." (PMID 40979705, 2025). "The cognitive impairment observed in these cases may be attributed to the activation of the renin-angiotensin system, induction of mitochondrial dysfunction and oxidative stress, and decreased ATP production in hippocampal cells." (PMID 39220736, 2024). "Additionally, renin–angiotensin system blocker was reported to be effective for preventing the progression of cognitive impairment in patients with CKD28." (PMID 35752646, 2022). "In addition, the inhibition of the renin-angiotensin system by angiotensin-converting enzyme inhibitors, angiotensin receptor blockers may be beneficial in alleviating cognitive deficits." (PMID 39980672, 2025). "In brain aging, an imbalance toward hyperactivation of the renin/ACE1/AngII/AT1R axis is observed, contributing to cognitive impairment and neuroinflammation." (PMID 40868980, 2025).
glioblastoma (13 papers, 2004 to 2024). The most malignant astrocytic tumor (WHO grade IV). "REN, which encodes the prorenin protein, was poorly expressed across the glioblastoma samples and, overall, had lower expression in glioblastomas compared to LGGs." (PMID 38607073, 2024). "Interestingly, high REN expression was significantly associated with poorer OS in glioblastoma cases after multivariate analysis (HR = 2.25 (1.05–4.8), p = 0.036), despite a non-significant trend after univariate Cox regression (HR = 1.53 (0.89–2.65), p = 0.13)." (PMID 38607073, 2024). "However, one renin-selective inhibitor could induce a rapid and important blockade of DNA synthesis, apoptosis and loss of viable cells in human glioblastoma cells in culture." (PMID 14997208, 2004). "Baseline expressions of RAS genes were relatively similar to the TCGA glioblastoma cohort, where REN and AGTR2 were very lowly expressed while ATP6AP2, AGTR1, ACE, and AGT were consistently expressed." (PMID 38607073, 2024). "The baseline mRNA expression of RAS genes (ATP6AP2, AGTR1, AGTR2, AGT, ACE, and REN) were explored in 12 patient-derived glioblastoma cell lines." (PMID 38607073, 2024). "The majority of CNAs of REN were amplifications across all PanCancer tumour types, where glioblastoma was ranked the third most common." (PMID 38607073, 2024). "ATP6AP2, AGTR1, AGTR2, AGT, and ACE had low frequencies of CNAs (<1%) in glioblastomas; however, REN was altered in 6% of glioblastoma cases." (PMID 38607073, 2024). "The combination of TMZ + RT resulted in a slight but significant increase in the expression of ATP6AP2, AGTR1, and ACE, while AGT and the lowly expressed AGTR2 and REN remained unchanged across all 12 glioblastoma cell lines." (PMID 38607073, 2024). "Here, we investigated the gene expression of RAS components (ATP6AP2, AGTR1, AGTR2, ACE, AGT, and REN) in glioblastoma patient samples from The Cancer Genome Atlas (TCGA) and their association with survival outcomes and the expression of TME pathways." (PMID 38607073, 2024). "A phase I clinical trial using repurposed renin–angiotensin system modulators to treat glioblastoma showed promising results, although the number of patients treated was low (n = 17)." (PMID 39063232, 2024). "Gliomas express peptides of the renin–angiotensin system, which plays a crucial role in the glioblastoma microenvironment." (PMID 39063232, 2024). "We studied the expression of RAS-related genes (ATP6AP2, AGTR1, AGTR2, ACE, AGT, and REN) in The Cancer Genome Atlas (TCGA) glioblastoma cohort, their relationship to patient survival, and association with tumour microenvironment pathways." (PMID 38607073, 2024). "Human glioblastoma cells express immunohistochemistry demonstrable renin and angiotensinogen mRNAs and proteins, as well as renin and angiotensin 1 or 2 receptors." (PMID 23594434, 2013). "The expression of angiotensinogen, (pro)renin, ACE, and AT1 and AT2 receptors has been demonstrated in glioblastoma tumours and glioblastoma cells in culture, in which renin has a direct role in proliferation and/or survival." (PMID 16755291, 2006). "The expression and function in growth and apoptosis of the renin–angiotensin system (RAS) was evaluated in human glioblastoma." (PMID 14997208, 2004). "Renin expression has been previously demonstrated by immunohistochemistry in human glioblastoma and AGT synthesis by Northern blotting in nontumoral (n=3) and tumoral (n=3) astrocytic cell lines." (PMID 14997208, 2004). "Human glioblastoma and glioblastoma cells expressed renin, AGT, renin receptor, AT2 and/or AT1 mRNAs and proteins determined by RT–PCR and/or Western blotting, respectively." (PMID 14997208, 2004). "Three renin inhibitors, pepstatin, remikiren and RO0663525, at increasing concentrations were used to evaluate for the functions of renin in glioblastoma cells." (PMID 14997208, 2004).